OR14A16 (olfactory receptor family 14 subfamily A member 16)
Description:
Odorant receptor.
Synonyms: OR5AT1
Tractability: Antibody: UniProt places it where antibodies can reach, with medium confidence; UniProt predicts a signal peptide or a membrane-spanning region; its Gene Ontology location is reachable by antibodies, with medium confidence.
Gene: Protein-coding gene on chromosome 1 (247,814,660 to 247,824,119, reverse strand). Ensembl gene ENSG00000196772.
Subcellular location: Cell membrane
Pathways (Reactome):
Sensory Perception: Expression and translocation of olfactory receptors
Gene Ontology:
Molecular function: odorant binding; olfactory receptor activity; G protein-coupled receptor activity
Biological process: sensory perception of smell; detection of chemical stimulus involved in sensory perception of smell; G protein-coupled receptor signaling pathway
Cellular component: plasma membrane; membrane
Genetic constraint (gnomAD): Loss-of-function variants: 1 observed, 0.42 expected, observed/expected ratio (o/e) 2.41. That is too few expected variants to judge how well the gene tolerates losing a copy. Missense variants: 333 observed, 366.57 expected, observed/expected ratio (o/e) 0.91, 90% interval 0.83 to 1. Synonymous variants: 127 observed, 138.85 expected, observed/expected ratio (o/e) 0.91, 90% interval 0.79 to 1.06.
Homologues: Orthologues: chimpanzee OR14A16 (97% identical). Paralogues in human: OR14A2 (55% identical), OR14I1 (53% identical), OR14J1 (51% identical), OR14L1 (50% identical), OR14K1 (50% identical), OR14C36 (49% identical), OR5B21 (44% identical), OR8H1 (44% identical), OR5AR1 (43% identical), OR8H3 (43% identical), OR5B12 (42% identical), OR8H2 (42% identical), and 84 more.